CRP (C-reactive protein)
Diseases named in the same sentence as CRP in open-access papers (continued):
Sharing a sentence is not in itself a finding about the gene and the disease.
Hypoalbuminemia (continued). "Patients having either chronic kidney disease or high CRP levels (more than 100 IU/l) or hypoalbuminemia could be identified as high-risk patients and treatment must be continued under close monitoring to pick up complications that may lead to mortality." (PMID 34285680, 2021). "Importantly, CAD patients with high hs-CRP levels (> 3 mg/L) and hypoalbuminemia (< 35 g/L) exhibited a three-fold increased risk of long-term all-cause mortality." (PMID 34961476, 2021). "Studies have demonstrated SIR, which is indicated by a high neutrophil-lymphocyte ratio (NLR), an elevated C-reactive protein (CRP) and Glasgow Prognostic Score (GPS) (i.e. the combination of elevated CRP and hypoalbuminemia), is associated with a poor prognosis in cancer patients." (PMID 35111685, 2021). "However, for the larger CA-BSI cohort we found a high negative correlation (R = −0.47, P < 0.0001) between 61 583 paired CRP and PA specimens, clearly indicating hypoalbuminemia as a marker of an underlying chronic inflammation." (PMID 32100658, 2020). "In addition to help diagnose incomplete KD, high CRP level and hypoalbuminemia have also been reported to be risk factors for CAL development in previous studies." (PMID 33324592, 2020). "Moreover, hypoalbuminemia and C-reactive protein (CRP) are associated with a poor prognosis in cancer patients." (PMID 28717855, 2017). "Other identified risk factors include hypoalbuminemia and elevated CRP." (PMID 27529033, 2016). "The present study investigated whether haematuria was associated with clinical outcomes in a stage 3–5 nondiabetic CKD cohort, revealing that haematuria was associated with proteinuria, hypoalbuminemia, and a high CRP." (PMID 26472621, 2015). "Additionally, it has been reported that increased CRP level was associated with factors that played important roles in PD patient survival, such as hypoalbuminemia, residual renal function, and peritoneal transport rate." (PMID 25961883, 2015). "Moreover, correlations were observed between haematuria and proteinuria, hypoalbuminemia, and an increased CRP, indicating an association between haematuria and inflammation status." (PMID 26472621, 2015). "Furthermore, the presence of an elevated C-reactive protein concentration and hypoalbuminaemia have also been shown to be associated with the upregulation of components of innate immune system, including complement and macrophage functions." (PMID 19209171, 2009). "A plausible explanation is that an elevated mGPS may reflect compromised cell-mediated immunity, as an elevated C-reactive protein and hypoalbuminaemia are associated with lymphocytopenia and with an impaired T-lymphocytic response in the tumour." (PMID 19209171, 2009). "Phase angle and s-albumin, together with additional biochemical nutritional and inflammatory parameters (i.e., s-CRP, IL-6), may help to monitor and adjust dry body weight in wasted HD patients, since hypoalbuminemia is also caused by hemodilution during states of chronic volume expansion." (PMID 35458220, 2022). "There are several possible pathways to explain the association between hypoalbuminemia, cardiogenic shock, outcome and the laboratory parameters associated with hypoalbuminemia in this study, such as lower hemoglobin and higher CRP-values, which may act in concert." (PMID 31095609, 2019). "Soft pancreatic texture, small duct diameter, hypoalbuminemia, elevated CRP, and prolonged operative time are significant independent predictors." (PMID 42281939, 2026). "Other laboratory parameters, such as electrolyte imbalance (p = 0.008; OR 2.213), elevated CRP (p = 0.164; OR 1.400), hypoalbuminemia (p = 0.218; OR 1.353), and decreased hematocrit (p = 0.192; OR 1.394), were also initially included for further analysis." (PMID 41153495, 2025).
Hypoalbuminemia (continued). "Of these predictors, namely, pre-hospitalization ibuprofen intake, infective focus elsewhere, hypoalbuminemia < 3.1 g/dL, serum CRP > 20 mg/dL, Hb < 10 g/dL and total leucocyte count > 10,000 cells/μL, at least three were in line with our univariate analysis." (PMID 40868554, 2025). "In the state of hypoalbuminemia, the human body is more prone to trigger systemic inflammatory responses and immune suppression,resulting in elevated levels of C-reactive protein (CRP) and interleukin-6 (IL-6) in the body." (PMID 40641962, 2025). "Myocarditis patients were also more likely to have high CRP (OR = 4.39), hypoalbuminemia (OR = 2.7), AST >45 (OR = 2.5), and haematocrit >45 (OR = 2.12), but these findings were not significant." (PMID 40535371, 2025). "Laboratory investigation revealed a positive polymerase chain reaction test for SARS-CoV-2 infection, elevated hemoglobin, acute kidney injury hypoalbuminemia, and moderately elevated C-reactive protein levels." (PMID 39931582, 2025). "Additional findings included hypoalbuminaemia (Alb 2.5 g/dL) and elevated inflammatory markers (C-reactive protein [CRP]: 21.0 mg/dL, ferritin: 2,138 ng/mL)." (PMID 40821825, 2025). "Although initial treatment resulted in a reduction in C-reactive protein (CRP) levels, bloody diarrhea persisted and hypoalbuminemia progressed (reference range: 3.8-5.3 g/dL)." (PMID 40726872, 2025). "In terms of nutritional assessment, patients with constipation, severe infection, chronic kidney disease, fever, high CRP, and hypoalbuminemia significantly increased risks of low HDL-C by 1.432, 2.496, 1.543, 3.056, 1.794, and 2.703 times, respectively." (PMID 40607030, 2025). "Blood tests, performed on the same day, showed neither leucocytosis nor hyper eosinophilia, clinical chemistry was normal (except for G1 hypoalbuminemia), and C-reactive protein (CRP) was slightly increased (5.7 mg/dL, ULN 5 mg/dL)." (PMID 40143296, 2025). "Laboratory findings showed transaminitis, hypoalbuminemia, elevated C-reactive protein, and mild hypokalemia, suggesting an infectious etiology." (PMID 40895922, 2025). "Following randomization, the patient subgroups showed comparable clinical characteristics, including similar serum CRP levels, hypoalbuminemia and low prealbumin levels." (PMID 41003011, 2025). "Laboratory findings included elevated leukocyte counts, CRP, and other indicators of infection, as well as decreased lymphocyte counts and hypoalbuminemia." (PMID 41341819, 2025). "Instead of delaying lifesaving treatment, the authors highlight the importance of recognizing iMCD early on based on laboratory data (elevated ALP, normal immunoglobulin levels, increased CRP, and hypoalbuminemia) and giving siltuximab as soon as possible." (PMID 41220922, 2025). "Laboratory tests revealed leukopenia, elevated C-reactive protein, abnormal liver enzymes, and hypoalbuminemia." (PMID 41366987, 2025). "Other stated findings were increased liver enzymes (aspartate and alanine transaminases, lactate dehydrogenase), hypoalbuminemia and hypofibrinogenemia, and high serum levels of triglycerides and ferritin, as well as D-dimer with C-reactive protein." (PMID 40572665, 2025). "In our patient, markedly elevated CRP (>90 mg/L), hypoalbuminemia, and transaminitis reflected a severe inflammatory response typical of complicated scrub typhus." (PMID 40895922, 2025). "CRF severity is associated with poorer quality of life and linked to malnutrition and inflammation, as reflected in higher PG-SGA scores, hypoalbuminemia, and elevated CRP levels." (PMID 40806017, 2025). "Elevated inflammatory markers (ESR 29 mm/h, CRP 267.69 mg/L), mild elevation of procalcitonin (0.27 ng/mL), and severe hypoalbuminemia (17.8 g/L) were noted." (PMID 40726983, 2025). "In the meantime, laboratory blood test showed increased CRP and transaminases, hyperferritinemia, hypoalbuminemia, and acute kidney injury." (PMID 40374837, 2025).
Hypoalbuminemia (continued). "Hypoalbuminemia provided the most added information, whereas CRP only marginally improved the models." (PMID 38477040, 2025). "This systematic evaluation of clinical evidence consistently identified hypoalbuminemia and elevated CRP-based scores as strong predictors of adverse outcomes." (PMID 41149486, 2025). "Our findings are consistent with prior studies showing that hypoalbuminemia and elevated CRP levels are independent predictors of adverse outcomes in older patients." (PMID 40944295, 2025). "Laboratory findings revealed elevated C-reactive protein (CRP) at 6.14 mg/L, hypokalemia with serum potassium at 3.10 mmol/L, and hypoalbuminemia with albumin levels at 39.3 g/L." (PMID 39931564, 2025). "In conclusion, Tac should be chosen for thiopurine‐naïve patients with relatively short disease duration, even for patients with hypoalbuminemia and high CRP values at the start of Tac." (PMID 40177188, 2025). "Laboratory findings showed marked hypoalbuminemia, elevated levels of serum creatinine, C-reactive protein (CRP), alkaline phosphatase (ALP), and soluble interleukin-2 receptor (sIL-2R)." (PMID 40351914, 2025). "The initial laboratory investigation showed acute kidney injury, hemoconcentration, hypoalbuminemia, and moderately elevated C-reactive protein levels." (PMID 39931582, 2025). "At baseline (T0), all inflamed patients enrolled in the study presented with elevated serum CRP levels, a predominance of innate over adaptive immunity (as indicated by a high N/L ratio), hypoalbuminemia and low prealbumin levels." (PMID 41003011, 2025). "Persistent CRP elevation, progressive hypoalbuminemia, and worsening general condition ultimately rendered surgical treatment unfeasible, and he succumbed to intestinal hemorrhage." (PMID 40726872, 2025). "Factors associated with lower HDL-C levels include nutritional risk, nausea, vomiting, constipation, pancreatic insufficiency, severe infections, chronic kidney disease, fever, high CRP, hypoalbuminemia, and parenteral nutrition." (PMID 40607030, 2025). "Laboratory parameters showed leucocytosis, elevated CRP, hypoalbuminemia, mild hypokalaemia, and hypophosphatemia." (PMID 41246573, 2025). "Based on similar AIC values, both hypoalbuminemia and its combination with CRP, as expressed in the GPS, emerge as possible stratification factors for future clinical trials and prognostic research." (PMID 38477040, 2025). "Conversely, patients with a history of severe infection, chronic kidney disease(CKD), fever, high CRP, and hypoalbuminemia have higher prevalence rates of low HDL-C levels at 51.9, 39.9, 57, 43, and 52.7%, respectively, all Ps<0.05." (PMID 40607030, 2025). "Older age, DM, smoking, hypoalbuminemia, higher CTGF, higher NT-proBNP and elevated hs-CRP were consistently associated with higher death risk." (PMID 41373510, 2025). "Certain surrogate markers of cachexia, such as hypoalbuminemia and elevated basal CRP levels during outpatient follow-up, have been correlated with increased mortality." (PMID 38611643, 2024). "Additional findings suggestive of HLH are raised levels of C-reactive protein (CRP) and D-dimer, and hyponatremia and hypoalbuminemia." (PMID 38541872, 2024). "The laboratory criteria include: “1” increased CRP and high sedimentation rate, “2” anemia, “3” thrombocytopenia or thrombocytosis, “4” hypoalbuminemia, “5” renal dysfunction or proteinuria, “6” polyclonal hypergammaglobulinemia." (PMID 39252787, 2024). "Laboratory investigations revealed various abnormalities, such as elevated white blood cell count, increased inflammatory markers (e.g., C-reactive protein), elevated liver enzymes, coagulation dysfunction, and hypoalbuminemia." (PMID 39949514, 2024). "Patients were stratified into the following three mGPS categories: 0 (normal CRP and albumin), 1 (elevated CRP or hypoalbuminemia), and 2 (elevated CRP and hypoalbuminemia)." (PMID 39156325, 2024).
Hypoalbuminemia (continued). "These patients also had higher CRP levels (11.3 vs. 4, p < 0.001), a greater degree of hypoalbuminemia (32.5 vs. 35, p < 0.001), lower oxygen saturation (92% vs. 94%, p < 0.001), and lower PaO2/FiO2 (266 vs. 281, p < 0.001)." (PMID 38475703, 2024). "Both patients had thrombocytopenia and hypoalbuminemia; an increased neutrophil ratio, procalcitonin, and C-reactive protein; and abnormal liver function and coagulation dysfunction." (PMID 38533387, 2024). "The upregulation of CRP production is invariably accompanied by a rapid decrease in blood albumin levels, leading to hypoalbuminemia." (PMID 39064000, 2024). "A significantly higher proportion of children with CD had abnormal CRP and hypoalbuminemia when compared to UC (94.3% vs. 55.6%, P < .001; and 62.9% vs. 36.1%, P = 0.004, respectively)." (PMID 38561705, 2024). "Our results are consistent with the research of other authors, which show that high levels of CRP and hypoalbuminemia are significant for the occurrence of severe forms of the disease, indicating the development of cytokine storms." (PMID 39599799, 2024). "One-third (10/30) of the patients in our cohort were affected by hypoalbuminemia, and almost all AP patients had CRP levels above 10 mg/L." (PMID 39594998, 2024). "Elevated levels of CRP, D-dimer and neutrophils, as well as hypoalbuminemia were found in most of the included children during the acute phase." (PMID 38178192, 2024). "In summary, serum CRP and albumin levels act as reliable biomarkers, while high serum CRP and hypoalbuminemia are independent prognostic factors in esophageal cancer and can predict the survival of patients with esophageal cancer to a certain extent." (PMID 39070256, 2024). "Liver metastasis, gastrointestinal cancer, hypoalbuminemia, elevated basal C-reactive protein, ECOG-PS greater than 2 at ICU admission, admission from ward and an APACHE II score over 14 were related to higher mortality." (PMID 38611643, 2024). "Patients with NYHA functional class IV had a lower hemoglobin, higher aspartate aminotransferase, higher prevalence of hypoalbuminemia, and higher CRP." (PMID 38314569, 2024). "Upon preliminary workup, 86.4% were found to be anemic, 86% had elevated ESR, 54.5% had raised CRP, and 22.7% had hypoalbuminemia." (PMID 38525201, 2024). "Within all 3 NAC disease subgroups, hyperbilirubinemia, hypoalbuminemia, high ALP, high CRP, hyponatremia, and troponin‐T >56 ng/L were associated with mortality." (PMID 38314569, 2024). "In other words, a high mGPS reflects both active systemic inflammation (elevated CRP level) and low nutritional status (hypoalbuminemia)." (PMID 36661734, 2023). "The blood tests revealed elevated C-reactive protein levels, immunoglobulin G, IL-6, and hypoalbuminemia in all patients, and the immunoelectrophoretic analysis confirmed polyclonal hypergammaglobulinemia." (PMID 37102781, 2023). "Compared to the zinc non-deficiency group (ZND group), patients with ZD group were significantly older, higher levels of CRP and hypoalbuminemia." (PMID 36607966, 2023). "After adjusting for hypoalbuminemia, and CRP, multivariate analysis showed that age and zinc level were independent predictors of baPWV." (PMID 36607966, 2023). "White blood cell counts over 20,000 cells/mm3, an increase in the C-reactive protein level and hypoalbuminemia were noticed only in three patients with strictures." (PMID 36836234, 2023). "In contrast, elevated serum levels of C-reactive protein and hypoalbuminemia were important indicators for adjusting the dry weight downward." (PMID 37386392, 2023). "Our analysis showed the importance of declining blood pressure during dialysis for predicting an upward change in the DW and the impact of elevated CRP levels and hypoalbuminemia on predicting a downward change in the DW." (PMID 37386392, 2023).
Hypoalbuminemia (continued). "In the mGPS, isolated hypoalbuminemia (<35 g/L) does not score; therefore, a mGPS score of 1 represents an isolated elevation of CRP (>10 mg/L), and a mGPS score of 2 represents an elevation of CRP with hypoalbuminemia." (PMID 36766755, 2023). "Laboratory findings showed hypoalbuminemia (66%), elevated CRP (92%), transaminitis (56%) and only 16% of patients had sterile pyuria." (PMID 37848930, 2023). "GPS includes scores of 0, 1, 2, with scores ≥2 signifying both hypoalbuminemia (<35 g/L) and elevated CRP levels (>10 mg/L)." (PMID 37213604, 2023). "Consistent with our conclusion, higher CAR, indicating hypoalbuminemia and elevated CRP levels, is related to worse survival in patients following HSCT." (PMID 36875097, 2023). "At the same time, patients with hypoalbuminemia had higher levels of CRP, leukocytes, LDH, and D-dimer and lower levels of lymphocytes and eosinophils." (PMID 36982882, 2023). "First, they suffered more frequently from hypoalbuminemia, thrombocytopenia and highest levels of inflammatory/severity markers such as hs-TnT, CRP, neutrophils to lymphocytes ratio and D-Dimer, all biomarkers associated with poor prognosis in ACS setting." (PMID 35951109, 2023). "At laboratory analysis on admission, they also showed more frequently hypoalbuminemia and higher serum values of CRP, AST, WBC count, neutrophils/lymphocytes ratio, D-Dimer, glucose, hs-TnT and CK-MB." (PMID 35951109, 2023). "As for labwork abnormalities in atypical KD, increased CRP, increased erythrocyte sedimentation rate, anemia, neutrophil leukocytosis, hypoalbuminemia, and hypertransaminasemia can be present in 25.4% of patients with atypical disease manifestations." (PMID 37189542, 2023). "In general, the HS-mGPS was defined as follows: Patients with both hypoalbuminemia (<35 g/L) and increased CRP levels (>3 mg/L), with one of these variables, and with none of these variables were assigned scores of 2, 1, and 0, respectively." (PMID 36674837, 2023). "Of note, female patients had more elevated C-reactive protein and more advanced hypoalbuminemia than the male patients." (PMID 37512020, 2023). "Hypoalbuminemia and high CRP levels are frequently observed in advanced cancer patients and are generally reported to be associated with worse survival." (PMID 37173358, 2023). "This cluster was characterized by the presence of hypotension/shock, high CRP, ferritin, D-dimer and NT-proBNP levels, liver enzyme abnormalities, hypoalbuminemia, thrombocytopenia, and ventricular dysfunction." (PMID 37046304, 2023). "Laboratory investigations revealed leukopenia, microcytic anemia, thrombocytopenia, hypoalbuminemia, and elevated levels of liver enzymes, C-Reactive Protein (CRP), Erythrocyte Sedimentation Rate (ESR), Lactate Dehydrogenase (LDH), and Ferritin." (PMID 36627589, 2023). "Laboratory findings revealed a normal haemogram, an elevated C-reactive protein (CRP) and sedimentation rate, normal renal function, hypoosmolar hyponatremia, hypoproteinemia, and hypoalbuminemia." (PMID 36570116, 2022). "Multivariate analysis revealed that insulin dependence, hypoalbuminemia (<33 g/L), elevated CRP (>150 mg/L), and LRINEC score of <6 were found to be associated with failed TMA." (PMID 36327256, 2022). "Upon admission, the severe patients displayed a marked elevation in acute-phase reactants including CRP and d-dimer, and hypoalbuminemia, suggesting ongoing immunological abnormalities." (PMID 35350784, 2022). "Generally, risk factors for biologic treatment in IBD (UC and CD together) were fever and fatigue at diagnosis, hypoalbuminemia, hypoproteinemia, and elevated CRP; hypoalbuminemia was the most significant predictor." (PMID 36291494, 2022). "Decreased LVEF, higher TAVR score, higher serum CRP level, hypoalbuminemia, higher CAR value and postprocedural acute kidney injury were associated with early mortality in univariate Cox regression analysis (P<0.05)." (PMID 35244369, 2022).